IL6 (interleukin 6)
Diseases named in the same sentence as IL6 in open-access papers (continued):
Sharing a sentence is not in itself a finding about the gene and the disease.
Hepatic steatosis (continued). "Hepatic steatosis can then induce or accelerate the disruption of the gastrointestinal tract via pro-inflammatory cytokines (e.g., TNF-α, IL-6, and IL-8) that promote tumor formation in the colon." (PMID 36548355, 2022). "In the process of hepatic steatosis, the production of proinflammatory mediators such as TNF‐α and IL‐6 contributes to the activation Kupffer cells." (PMID 33720453, 2021). "Given the relationship between the severity of hepatic steatosis and cytokines, the expression of TNF-α was more concomitant with the severity of hepatic steatosis than that of IL-6." (PMID 33388967, 2021). "The enhanced hepatic steatosis and fibrosis observed in HFD PN + HFD male offspring were accompanied by an increased expression of Mcp-1 and a decreased expression of Il-6." (PMID 34977118, 2021). "But in Sirt1+/− mice on HFD, body weight, fat content and hepatic steatosis are increased, adipose tissue macrophage infiltration and expression of inflammatory genes, indicated by the expression of F4/80, TNF-α, IL-1, and IL-6, are enhanced in epididymal fat." (PMID 33390968, 2020). "Studies elucidating the role of IL6 and its inhibition have revealed the detrimental role of this cytokine in the processes of WAT browning and hepatic steatosis." (PMID 33251224, 2020). "Conversely, both UCP1−/− and IL-6−/− mice that were protected from both burn-induced WAT browning and hepatic steatosis, also showed reductions in hepatic ER stress." (PMID 31740668, 2019). "Deletion of interleukin 6 (IL-6) and the uncoupling protein 1 (UCP1), regulators of burn-induced WAT browning completely protected mice from hepatic steatosis after the injury." (PMID 31740668, 2019). "Our results demonstrate a direct connection with the lower expression of pro-inflammatory IL-6 and increase of anti-inflammatory IL-10, and lower values of AST with the reduction of hepatic steatosis." (PMID 31861497, 2019). "Inhibition of the upstream regulator (IL-6) and the downstream regulator (UCP-1) of burn-induced browning protected mice from the development of hepatic steatosis." (PMID 31740668, 2019). "Together, these findings provide compelling evidence that inhibition of burn-induced browning via the deletion of either the upstream or downstream regulators, IL-6 and UCP-1, respectively, attenuates burn-induced hepatic steatosis." (PMID 31740668, 2019). "Flaxseed oil rich in ALA intervention apparently decreased the serum level of inflammatory cytokines (IL-6, IL-1β, MCP-1, and TNF-α) and attenuated hepatic steatosis by regulating ER stress." (PMID 33273997, 2019). "When combined as a biomarker panel in an algorithm; IL-6, adiponectin and cytokeratin 18 (CK18) displayed an AUROC of 0.90 with sensitivity and specificity of 85% and 86% respectively for discriminating fatty liver alone from NASH." (PMID 31291245, 2019). "There is a characteristic cytokine pattern in liver steatosis such as the increase in TNF-α and IL-6." (PMID 30158441, 2018). "In comparison with placebo, GC significantly increased Sirt1 and decreased hs-CRP, TNF-α, IL-6, ALT, and the degree of fatty liver (P < 0.05)." (PMID 30263038, 2018). "GC supplementation in obese NAFLD patients reduced inflammatory biomarkers (IL-6, TNF-α, and hs-CRP), ALT, and the degree of fatty liver and increased Sirt1 compared with placebo." (PMID 30263038, 2018). "ACR and ARB reduced the hepatic expression levels of Tnfa, Il6, and Il1b mRNA in OLETF rats with improved hepatic steatosis." (PMID 30477453, 2018). "Here we demonstrate that Arg-II−/− mice reveal decreased hepatic steatosis, macrophage infiltration, TNF-α and IL-6 as compared to the wild type (WT) littermates fed high fat diet (HFD)." (PMID 26846206, 2016). "In the same model as ours, linagliptin alleviates hepatic steatosis and inflammation by reducing macrophages infiltration and lobular inflammation, as well as expression of TNF-α and IL-6." (PMID 27462372, 2016).
Hepatic steatosis (continued). "In some models of fatty liver disease, high doses of human IL-6 ameliorate the liver steatosis, whereas restoration of IL-6 in DIO IL-6-/- mice up-regulates hepatic lipogenic enzymes and aggravates steatosis." (PMID 27333268, 2016). "The MAS score and levels of pro-inflammatory markers, including IL-6, IL-1β, and TNF-α, were significantly decreased following EA administration, demonstrating the compound's efficacy in attenuating hepatic steatosis and inflammation in a dose-responsive manner." (PMID 41530836, 2026). "We evaluated IL-6, IL-18, and TNF-a because these might promote intra-hepatic lipid peroxidation and peripheral lipolysis, which could contribute to development of hepatic steatosis." (PMID 40700400, 2025). "In addition, overexpressing IREB2 increased IL-1β, IL-6, and TNF-α, promoting HFD-induced metabolic disorders, hepatic steatosis, and inflammation." (PMID 39910919, 2025). "Cytokines, particularly interleukin (IL)-6, IL-18, and tumor necrosis factor (TNF)-α, could promote intra-hepatic lipid peroxidation and peripheral lipolysis, contributing to hepatic steatosis." (PMID 40700400, 2025). "In addition to conventional metabolic indicators (ALT, AST, hepatic steatosis index), objective data from polysomnography (PSG) (AHI, blood oxygen saturation), and inflammatory markers (IL-6, TNF-α) will be integrated." (PMID 40140484, 2025). "In contrast, the addition of Hon to the Fru-enriched drinking water diminished the development of fatty liver and inflammatory processes, such as the increase in the number of neutrophils and MPO activity, as well as of PAI-1 and IL-6 protein concentration in liver tissue." (PMID 39987978, 2025). "The study, which involved an approximate intake of 50 g per day, found an increase in hepatic steatosis and no significant changes in inflammation markers such as IL-6, IL-8 and Cytokeratin-18 (CK-18)." (PMID 41010458, 2025). "Additionally, elevated IL-6 and CRP levels are known to suppress hepatic glycolysis and contribute to fatty liver disease progression." (PMID 40507158, 2025). "Other studies also reported elevation of IL-6, but not TNFα and IL-1β, as a compensatory mechanism that prevents the development of hepatic steatosis at the early stage of NAFLD." (PMID 38590904, 2024). "It was found that a heightened level of hepatic steatosis exhibited a notable correlation with an increased VAT/SAT ratio and HOMA-IR index and elevated levels of interleukin 6 (pg/mL) and interleukin 1β (pg/mL), coupled with reduced levels of matrix metalloproteinase 2 (ng/mL—nanograms/milliliter)." (PMID 38732626, 2024). "Compared to controls, AAA-1-immunized mice showed higher plasma CK-18 (5.3 vs. 2.1 pg/mL, p = 0.031), IL-6 (13 vs. 6.9 pg/mL, p = 0.035), IL-10 (27.3 vs. 9.8 pg/mL, p = 0.007), TNF-α (32.1 vs. 24.2 pg/mL, p = 0.032), and liver steatosis (93.4% vs. 73.8%, p = 0.007)." (PMID 39595946, 2024). "Compared to their wild-type counterparts, mice lacking IL-6 showed reduced lobular inflammation while having a similar level of hepatic steatosis." (PMID 38535313, 2024). "However, they induced dose–response protective and ameliorative effects on the degree of hepatic steatosis, liver damage, and circulatory levels of ALT, AST, GTT, TNF-α, FFAs, and IL-6." (PMID 38004149, 2023). "Additionally, long-term HFD intervention in rats efficiently induced NASH as demonstrated by hepatic steatosis and inflammation, together with the increase in serum AST, ALT, and ALP levels and inflammatory-related gene expression of Il6 and Tnf." (PMID 36432581, 2022). "In addition to oxidative stress, inflammation mainly contributes to liver disease and pro-inflammatory factors such as IL6 and TNF-α significantly increase fatty liver disease." (PMID 36159326, 2022). "In addition to TGF-β, other cytokines, such as IL-1, IL-6, and TNF-α, contribute significantly to the pathophysiology of hepatic steatosis through stimulation of hepatic inflammation, and can in turn promote CRLM." (PMID 33767997, 2021).
Hepatic steatosis (continued). "In addition, they produced IL-6-KO mice and found that IL-6-KO mice reduced the browning of WAT by inhibiting STAT3 phosphorylation, accompanied by disturbed glucose homeostasis and accelerated hepatic steatosis." (PMID 34768943, 2021). "Loss of TKT in the liver increased apoptosis, reduced cell proliferation, decreased TNF-α, IL-6, and STAT3 levels, and alleviated DEN/HFD-induced hepatic steatosis and fibrosis, highlighting a key role for TKT in promoting genome instability during liver injury and tumor initiation." (PMID 32913470, 2020). "Furthermore, hepatic steatosis and levels of TNF-α, IL-6, IL-1β inflammatory genes increased in OVX rats, but were reduced after BCE intake." (PMID 32466275, 2020). "Supplementation of dietary-induced, obese mice with PSO improved both the mitochondrial function and dynamics in hepatic steatosis by decreasing the levels of inflammatory markers, NOV, IL-6, and phosphorylated P65, which is a major regulator of IKKβ/NF-KB signaling." (PMID 32751794, 2020). "A previous report found that a similar phenotype of liver steatosis did not induce significant changes in inflammatory mediators, such as Il-6, Tnf-α, or Il-1β." (PMID 33391254, 2020). "Furthermore, depletion of white adipose tissue messenger RNA levels of MCP-1, TNF-α, and IL-6; serum concentrations of TNF-α, IL-6, and MCP-1; macrophage infiltration in adipose tissue; and attenuation of liver steatosis were observed." (PMID 32318236, 2020). "For example, dietary supplementation with whole walnuts resulted in a significant decrease in macrophage infiltration and suppression of pro-inflammatory gene expression (tumor necrosis factor; TNF-α, interleukin-6; IL-6 and IL-10) in a mouse model of high-fat diet (HFD)-induced fatty liver disease." (PMID 31137456, 2019). "Wang further found that the injection of recombinant murine FGF21 reduces IL-6, TNF-α, and leptin mRNA levels in WAT of monosodium glutamate-induced obese rats, with the improvement of glucose tolerance, lipid metabolic spectrum, and hepatic steatosis." (PMID 27616737, 2016). "Additionally, elevated levels of chronic inflammation markers, such as interleukin-6 (IL-6) and tumor necrosis factor-alpha (TNF-α), along with reduced secretion of muscle-derived factors, may further contribute to hepatic steatosis and liver inflammation." (PMID 40433168, 2025). "Hepatic steatosis perturbs mitochondrial homeostasis and activates nuclear factor kappa B (NF-κB), thereby amplifying inflammatory cascades and inducing the release of cytokines such as tumor necrosis factor-α (TNF-α), interleukin-6 (IL-6), and interleukin-1β (IL-1β)." (PMID 41150795, 2025). "The authors showed that the mice increased fat weight, hepatic steatosis, inflammation, multifocal necrosis, and alanine aminotransferase (ALT) and aspartate aminotransferase (AST) levels, along with pro-inflammatory cytokines such as endotoxin and interleukin-6 (IL-6)." (PMID 40507175, 2025). "Results: the HFHS diet induced, in the dams, hepatic steatosis, oxidative stress (reduced catalase, elevated protein oxidation) and the activation of pro-inflammatory pathways (p38-MAPK), along with imbalanced circulating cytokine concentrations (increased IL-6 and decreased IL-5 and IL-17A)." (PMID 38671859, 2024). "CSF treatment improved the hepatic steatosis, intralobular inflammation, and balloon-like changes while decreasing the lipid deposition in HFD rats by decreasing the levels of TG, AST, and ALT and down-regulating the expression of TLR4, MyD88, NF-κB, TNF-α, IL-6, as well as IL-8." (PMID 37762063, 2023). "Pro‐inflammatory response in hepatic steatosis may be promoted by various stimuli, such as liver enzymes (ALT, AST), oxidative stress, total cholesterol, and triglycerides, and is characterized by increases of TNF‐ɑ and IL‐6 in the liver." (PMID 36789034, 2023).
Hepatic steatosis (continued). "Furthermore, other chemokines, whose expression is mediated by the secretion of IL-6 from AT, such as JNK1, are involved in the development of hyperinsulinemia, hepatic steatosis and hepatic IR, demonstrating AT-derived IL-6 regulated distal metabolic effects on the liver." (PMID 37175497, 2023). "Thus far having shown that removing genes (IL-6, UCP-1) involved in post-burn WAT browning protected mice from hepatic steatosis, we wanted to determine if we could attenuate this adverse post-burn response therapeutically in wild type mice." (PMID 31740668, 2019). "Clinical studies examining patients with hepatic steatosis or NASH found supplementation, twice daily, with L-TRP for 14 months result in decreased plasma LDL, TG, and gamma gluthamylo transpeptidase levels with a correlative decrease in plasma IL-1β, IL-6, and TNF." (PMID 31921154, 2019). "To evaluate STAT3 and miR21 implication in liver steatosis also in vivo, we treated 5 weeks aged C57/BL6 mice for 72 weeks with metformin, an established anti-diabetic drug, that is able to modulate STAT3 signaling by repressing IL-6-dependent phosphorylation of STAT320,21." (PMID 30206377, 2018). "Taking into account that hepatic PLZF overexpression induces hepatic steatosis and PLZF plays a crucial role in the natural killer cell function, we hypothesized that overexpression of PLZF will increase the contents of intrahepatic pro-inflammatory cytokine TNFα and IL-6." (PMID 36438786, 2022). "Our findings demonstrate that inflammatory and metabolic stress pathways, including TNF, IL-6, IL-1β, and MAPK13 signaling, promote the progression of hepatic steatosis to MASH and fibrosis under KD at TN but not at RT." (PMID 40864559, 2025). "DHA suppressed acute ethanol-induced hepatic steatosis and downregulated the levels of stearoyl-CoA desaturase 1 (SCD) and inflammatory cytokines, such as TNF-α and IL-6, but did not affect reactive oxygen species production." (PMID 38791514, 2024). "The absence of IL-6 or STAT3 signaling in chronic liver inflammation enhanced HCC development, leading to an increase in hepatic steatosis, macrophage accumulation, and hepatocyte proliferation." (PMID 37627184, 2023). "In addition, we also found that the mRNA levels of hepatic proinflammatory cytokines such as IL-6 and IL-1β were significantly downregulated in VPA group relative to control group S2 Fig, suggesting that VPA-caused liver steatosis and oxidative stress might not be associated with the inflammation." (PMID 37971986, 2023). "Despite obvious increased hepatic steatosis in HC-HMGB1−/−mice early, serum levels of ALT (marker of liver injury) and IL-6 (systemic inflammation) were not significantly higher compared to controls mice until 16 weeks." (PMID 33238880, 2020).
cognitive decline (279 papers, 2010 to 2026). "IL‐6 emerged as a key pro‐inflammatory marker linked to neurodegenerative diseases and cognitive decline, showing stronger correlations in African ancestry populations compared to Caucasians." (PMID 40709483, 2025). "The trials showed an increase in interferon gamma (IFN-γ) and CSF eotaxins, which are associated with a slower cognitive decline in AD patients and a decrease in interleukin 6 (IL-6), which is associated with inflammatory states." (PMID 40725728, 2025). "Among them, levels of chronic inflammatory factors such as CRP and IL-6 are associated with cognitive decline." (PMID 40809769, 2025). "In fact, increased BMI is related to the elevation of inflammatory proteins only in women, including C-reactive protein and interleukin-6, which can cause rapid cognitive decline due to an active inflammatory condition." (PMID 40114234, 2025). "Alterations in inflammatory markers such as interleukin-6 (IL-6) and C-reactive protein are associated with cognitive decline." (PMID 41150102, 2025). "The study found that higher IL-6 levels were associated with greater cognitive decline across domains such as memory and processing speed over a 3-year period." (PMID 40805992, 2025). "Inflammation appeared to play a prominent role, with several studies demonstrating that higher levels of inflammatory markers, such as CRP and interleukin-6, were linked to both social adversity and cognitive decline." (PMID 41278514, 2025). "Inflammatory markers, such as interleukins (IL-6 and IL-8), have been linked to cognitive decline in mood stabilizer users." (PMID 39377784, 2025). "Elevated levels of inflammatory markers (e.g., CRP, interleukin-6 (IL-6), tumor necrosis factors) are related to cognitive decline and increased risk of AD/ADRD, found both in the peripheral blood and cerebral spinal fluid (CSF)." (PMID 41440093, 2025). "Elevated levels of inflammatory markers, such as C-reactive protein (CRP) and interleukin-6 (IL-6), have been linked to cognitive decline in antidepressant users." (PMID 39377784, 2025). "Of particular interest, the level of serum IL-6 was significantly decreased in both aged IKD and KD mice, and a lower level of IL-6 has been associated with a reduced risk of experiencing cognitive decline with aging." (PMID 36933143, 2023). "The data from longitudinal studies suggested that levels of IL-6 significantly increased the risk of cognitive decline [OR = 1.34, 95% CI (1.13, 1.56)]." (PMID 36815174, 2023). "Elevated cerebrospinal fluid and plasma levels of Tumor Necrosis Factor-alpha (TNFa) and Interleukin-6 (IL-6) in AD patients predict further cognitive decline and have been linked to worse cognitive performance in both MCI and AD patients." (PMID 36900708, 2023). "Studies show that elevated cytokines, such as IL-6, can cause impairment and cognitive decline in the elderly." (PMID 37239991, 2023). "Aging-associated inflammatory cytokines, such as IL-6 and TNFα, were found to disrupt circuits that are involved in cognitive decline or dementia." (PMID 36615907, 2023). "Patients in the highest quartile of IL-6 level had a higher risk of cognitive decline than those in the first quartile, after adjusting for potential risk factors." (PMID 36547090, 2022). "High levels of IL-6 are associated with cognitive decline and memory impairments, and in AD patients, serum and CSF levels of IL-6 are up-regulated and considered as a marker of inflammation." (PMID 34445419, 2021). "Further investigation of these associations in older cohorts and those with longitudinal measures available would help to clarify the relationship, and additionally establish if the DNAm IL-6 score associates with cognitive decline." (PMID 33595649, 2021). "Systemic inflammatory markers such as C-reactive protein, tumor necrosis factor-alpha (TNF-a), and interleukin-6 (IL-6) are all implicated in cognitive decline." (PMID 34439769, 2021).